GPR55 (G protein-coupled receptor 55)
Diseases named in the same sentence as GPR55 in open-access papers (continued):
Sharing a sentence is not in itself a finding about the gene and the disease.
depression (12 papers, 2013 to 2025). "LPI and GPR55 are implicated as potential key modulators of stress responses, depression, motor functions, and memory in the central nervous system, since GPR55 is highly expressed in the cortex, hippocampus, striatum, and spinal cord." (PMID 32121640, 2020). "To summarize, these studies suggest that exposure to stress-induced depression results in decreased levels of GPR55 in a region-dependent manner and that the GPR55 agonist has antidepressant effects on behavior." (PMID 35628337, 2022). "There is evidence that GPR55 plays an important role in depression; a 7-day intravenous (i.v.)treatment with the GPR55-agonist O-1602 decreased despair-like behavior in female rats subjected to a 14-day corticosterone treatment." (PMID 35628337, 2022). "GPR55, as part of the endocannabinoid system, has gained interest in relation to the pathogenesis of various neurological and psychiatric disorders, and different studies demonstrate its relevance for disorders such as AD, PD, and depression." (PMID 38931342, 2024). "Therefore, several in vivo studies support the anti-depressive and anxiolytic effects of GPR55 activation in different mouse models of chronic stress and depression-like behavior." (PMID 38796643, 2024). "A 10-day chronic social defeat stress lowered hippocampal GPR55 levels in mice that were susceptible to the model (i.e., showed elevated levels of depression and anxiety), but not in resilient mice." (PMID 35628337, 2022). "Nevertheless, the modulation of inflammation by GPR55 might be a new therapeutic option to treat CNS disorders with a neuroinflammatory background such as AD or depression." (PMID 33801492, 2021). "Furthermore, GPR55 is also investigated for its role in depression." (PMID 38931342, 2024). "Additionally, we tried to determine the influence of GPR55 stimulation on the bladder, hippocampal and urine levels of several biomarkers that play a role in the functioning of the urinary bladder and/or the pathophysiology of depression." (PMID 32733244, 2020). "The down regulation of G protein-coupled receptor 55(GPR55) in chronic social defeat stress (CSDS) may mediate depressive-like phenotypes, and EA alleviates CSDS-induced depression-like behavior, an effect that is reversed by a GPR55 antagonist." (PMID 39367470, 2024). "However, since the authors excluded suicide victims with a history of depression or proof of antidepressants in their body fluids, no conclusions about the role of GPR55 in depression can be drawn from this work." (PMID 38796643, 2024).
epilepsy (11 papers, 2020 to 2025). A brain disorder characterized by episodes of abnormally increased neuronal discharge resulting in transient episodes of sensory or motor neurological dysfunction, or psychic dysfunction. "Thus, we examined the functional implications of these observations by investigating the impact of heterozygous genetic deletion of Gpr55 on the epilepsy phenotype of F1.Scn1a+/- mice." (PMID 36701411, 2023). "Collectively, these data suggest that inhibition of GPR55 might provide a new anticonvulsant drug target for intractable childhood epilepsies." (PMID 36701411, 2023). "The present study aimed to determine whether Gpr55 affects the epilepsy phenotype of F1.Scn1a+/- mice to infer its potential as a new drug target for the treatment of Dravet syndrome." (PMID 36701411, 2023). "Future studies in preclinical epilepsy models are needed to assess whether GPR55 and T-type calcium channels are necessary for the anticonvulsant effect of these phytocannabinoids." (PMID 36386164, 2022). "We also examined whether olivetolic acid and CBGA methyl ester retain activity at the epilepsy-relevant drug targets of CBGA: G-protein-coupled receptor 55 (GPR55) and T-type calcium channels." (PMID 34980287, 2022). "The orphan/atypical GPCRs (GPR55, GPR119, and GPR18) carry links to epilepsy and inflammatory hyper-excitability (GPR55), incretin biology and insulin release (GPR119), and tone in blood vessels with traffic of leukocytes (GPR18)." (PMID 41303442, 2025). "From experimental models of epilepsies, different CBD mechanisms have emerged, such as antagonism of G protein-coupled receptor 55 (GPR55), desensitization of transient receptor potential of vanilloid type 1 (TRPV1) channels, and interactions with voltage-gated sodium and potassium channels." (PMID 35418935, 2022).
colorectal cancer (10 papers, 2016 to 2025). A primary or metastatic malignant neoplasm that affects the colon or rectum. "Growing evidence has demonstrated that GPR55 is overexpressed in numerous malignancies, including breast and colorectal cancers, endometrial and squamous cell carcinomas." (PMID 36291926, 2022). "In GPR55 knockout mice (GPR55-/-), NF-κB levels are decreased in a mouse model of colorectal cancer." (PMID 33801492, 2021). "Mechanically, although GPR55 does not have a CpG island, its DNA methylation is globally reduced in colorectal cancer, which may contribute to the elevated transcription of GPR55 gene." (PMID 36291926, 2022). "In another system, similar opposing effects of the CB1 receptor (as a tumor suppressor) to GPR55 (as an oncogene) have been documented, in which DNA methylation of the CNR1 and GPR55 genes were also differentially regulated in samples from patients with colorectal cancer compared to control samples." (PMID 35666403, 2022). "Furthermore, GPR55 knockout mice (GPR55-/-) revealed a decrease in COX-2 levels in a mouse model of colorectal cancer, using azoxymethane and dextran sulfate sodium." (PMID 33801492, 2021). "However it was also recently shown that CB1 and GPR55 play opposing roles in colorectal cancer models in mice." (PMID 31289609, 2019). "In colorectal cancer, the selective antagonist CID16020046 impairs cell adhesion and migration in vitro and reduces liver metastases in vivo, supporting a role for GPR55 in tumor cell dissemination." (PMID 40434517, 2025). "As an inhibitor of GPR55, CBD significantly reduces the adhesion and migration of colorectal cancer cells to endothelial cells and reduces the metastasis of cancer cells in the liver in a mouse colorectal cancer metastasis model." (PMID 38397045, 2024). "Functional studies have indicated that LPI profoundly promotes migration/invasion of breast and colorectal cancer cells, which could be blocked by GPR5 antagonist or GPR55 knockdown." (PMID 36291926, 2022). "In a mouse model of colorectal cancer, the levels of COX-2 and PGF2α were decreased in GPR55−/−." (PMID 30453998, 2018).
atherosclerosis (9 papers, 2015 to 2025). A disease characterized by the build-up of fatty material and calcium deposition in the arterial wall resulting in partial or complete occlusion of the arterial lumen. "G-protein-coupled receptor 55 (GPR55) signaling has been reported to associate with atherosclerosis progression." (PMID 37544935, 2023). "In addition, to clarify the molecular mechanism of how lysoPtdGlc and GPR55 are involved in the progression of atherosclerosis, further detailed analysis is needed in an atherosclerosis model using GPR55-deficient mice." (PMID 37544935, 2023). "The involvement of LPIs and GPR55 in adiposity, hepatic steatosis, and atherosclerosis has been previously elucidated." (PMID 39000464, 2024). "Further studies on the molecular mechanisms involving lysoPtdGlc/GPR55 signaling in M2c macrophage-mediated atherosclerosis progression are warranted." (PMID 37544935, 2023). "In contrast, in our proposed advanced atherosclerosis model, foam cell formation is promoted by lysoPtdGlc/GPR55 signaling." (PMID 37544935, 2023). "Our findings suggest that lysoPtdGlc/GPR55 signaling is a potential therapeutic target for inhibition of atherosclerosis progression." (PMID 37544935, 2023). "GPR55 is highly expressed in human inflammatory cells (monocytes and macrophages) during atherosclerosis initiation and progression." (PMID 37544935, 2023). "GPR55 is highly expressed in human monocytes, which are important inflammatory cells during the initiation and progression of atherosclerosis." (PMID 34884889, 2021). "In summary, this study provides important evidence that GPR55 blockage markedly inhibits HFD-induced atherosclerosis development and improves HFD-induced lipid profiles." (PMID 34884889, 2021). "For instance, PEA (3 mg/kg/day), acting via GPR55 and PPARα in early atherosclerosis stabilized plaque in pre-established phase of the disease in mice." (PMID 32316328, 2020). "When compared to the "classical" CB1 and CB2 receptors, the effects exerted by GPR55 in atherosclerosis are similar to those of the former and opposite to those of the latter receptor." (PMID 25970609, 2015). "GPR55-mediated functions of M2c macrophages may thus change from PEA-dependent anti-inflammatory effect to lysoPtdGlc-dependent promoting effect on atherosclerosis development." (PMID 37544935, 2023). "Thus, in this study, the stimulatory roles of GPR55 in atherosclerosis, especially monocyte adhesion to the vascular endothelium and high-fat diet (HFD)-induced plaque formation, were investigated." (PMID 34884889, 2021). "The blockage of GPR55 by CID16020046 in vivo protects against atherosclerosis progression." (PMID 34884889, 2021). "In addition, GPR55 role in regulating neutrophil degranulation in atherosclerosis was demonstrated in rodent model by the use of GPR55 antagonist CID16020046 (0.5 mg/kg 5 times a week)." (PMID 32316328, 2020). "Taken together, our study suggests that GPR55 could be a novel pharmacological target to combat atherosclerosis and other related cardiovascular diseases." (PMID 25970609, 2015). "Studies using the GPR55 antagonist CID16020046 and agonists (AM251 and Abn-CBD) in ApoE-/- mice models of atherosclerosis revealed that GPR55 modulation affects neutrophil function depending on atherogenic progression and diet." (PMID 40599866, 2025). "For this purpose, we employed monocyte adhesion to human umbilical vein endothelial cells (HUVECs) and HFD-induced atherosclerosis development in ApoE knockout (KO) mice along with O-1602 as a GPR55 agonist and CID16020046 as a specific GPR55 antagonist." (PMID 34884889, 2021). "The role of GPR55 in monocyte adhesion and atherosclerosis development was investigated in human THP-1 monocytes and ApoE−/− mice using O-1602 (a potent agonist of GPR55) and CID16020046 (a specific GPR55 antagonist)." (PMID 34884889, 2021).
atherosclerosis (continued). "It has been suggested that cannabinoid-induced activation of G-protein coupled receptor 55 (GPR55) results in increased IL-12 and TNF-α, which in turn raises endocytic activity in monocytes, potentially leading to foam cell formation and atherosclerosis." (PMID 30294730, 2017). "Although pro-atherogenic functions of GPR55 in endothelial cells and macrophages have been studied, the role of GPR55 in monocyte adhesion and atherosclerosis development has not yet been investigated." (PMID 34884889, 2021). "Our data suggest that GPR55 could play deleterious role in ox-LDL-induced foam cells and could be a novel pharmacological target to manage atherosclerosis and other related cardiovascular diseases." (PMID 25970609, 2015).
diabetes (8 papers, 2011 to 2026). "GPR55, a paracannabinoid receptor, has been implicated in systemic metabolic regulation and in diseases such as intractable epilepsy, diabetes, and cancer." (PMID 41957642, 2026). "GPR55 is another GPCR, known as an LPI receptor and a putative endocannabinoid receptor, and is a peripheral target for diabetes treatment because GPR55 agonists have insulinotropic activity." (PMID 32121640, 2020). "Despite this, these findings suggest that LPI/GPR55 regulate insulin secretion, and that drugs that target GPR55 may be used in the treatment of diabetes." (PMID 21904624, 2011). "Several novel fatty acid receptors, including GPR55 and GPR119, have shown promise as emerging targets of diabetes therapies." (PMID 27677765, 2016). "In conclusion, long-term administration of GPR55 agonist Abn-CBD and GPR119 agonist AS-1269574 improved glycaemic control in a multiple-low-dose STZ-induced mouse model of diabetes, resulting in decreased plasma glucose and glucagon and improved plasma insulin, GLP-1 and lipid profiles." (PMID 27677765, 2016). "Interestingly, few studies have assessed the role of GPR55 in diabetes, with no literature probing the involvement of incretin hormones in the mechanism of action of GPR55." (PMID 27677765, 2016).
ovarian carcinoma (8 papers, 2015 to 2023). A malignant neoplasm originating from the surface ovarian epithelium. "ABCC1 has previously been linked to GPR55 in a feedback loop, where ABCC1 exports LPI, which binds to and activates GPR55, leading to downstream signaling, and this was implicated as important for prostate and ovarian cancer cell proliferation." (PMID 33081264, 2020). "In addition to affecting the tumour cells directly, LPI derived from ovarian cancer cells and ovarian cancer cell lines cause endothelial cell proliferation through binding to GPR55 causing activation of ERK1/2 and p38." (PMID 34324032, 2021). "Recent studies involving humans have indicated that L-α-lysophosphatidylinositol, a GPR55 agonist, induced endothelium-dependent vasorelaxation in the pulmonary arteries and mediated ovarian carcinoma cell-induced angiogenesis." (PMID 36937015, 2023). "For example, LPI and its 2-arachidonolyl lysophosphatidylinositol (2-ALPI) derivative, are the most potent ligands for GPR55 with the latter being markedly elevated in ascites fluid from ovarian cancer patients." (PMID 34324032, 2021). "Since ovarian epithelial cancer cells also express GPR55, then a positive feed-forward activation of cell proliferation is postulated." (PMID 34324032, 2021). "Together, these results suggest that LPI produced by ovarian cancer cells induces angiogenesis in a GPR55-dependent manner." (PMID 25989290, 2015). "We conclude that inhibiting the pro-angiogenic LPI/GPR55 pathway appears a promising target against angiogenesis in ovarian carcinoma." (PMID 25989290, 2015). "Selective inhibition of the LPI receptor GPR55 with CID16020046 (20 μM) effectively blocked ovarian cancer-induced angiogenesis of all tested cell lines." (PMID 25989290, 2015). "Highly vascularized ovarian carcinoma secretes the putative endocannabinoid and GPR55 agonist, L-α-lysophosphatidylinositol (LPI), into the circulation." (PMID 25989290, 2015). "Furthermore, the LPI-mediated activation of GPR55 promotes proliferation of ovarian and prostate cancer cells and ovarian-cancer-cell-induced angiogenesis, via activation of Akt, ERK1/2, and p38 MAPK pathways." (PMID 36291926, 2022). "Furthermore, LPI produced by ovarian cancer cells promotes angiogenesis, which is prevented by GPR55 inhibition or GPR55 knockdown." (PMID 36291926, 2022). "Further, we propose that the GPR55 antagonism (e.g. by CID16020046) could be of potential interest to develop an anti-tumour angiogenesis treatment (e.g. for patients with ovarian carcinoma)." (PMID 25989290, 2015). "The demonstration that GPR55 expression in EC tissue is enhanced in a way that favours the support of EC cell survival and proliferation and especially in more aggressive tumour types, similar to that observed for ovarian cancer suggests a possible pivotal role for this receptor in EC pathogenesis." (PMID 34324032, 2021). "This is especially important since elevated expression of GPR55 and the production of its two most cogent ligands LPI and 2-ALPI have already been demonstrated to be important in the development of ovarian cancer." (PMID 34324032, 2021). "Hofman and colleagues more recently found that elevated lysophosphatidylinositol levels in the ovarian cancer cell lines OVCAR-3, OVCAR-5, and COV-362 resulted in GPR55-dependent angiogenesis." (PMID 33375539, 2020). "Our group demonstrated that GPR55 has a key role in cancer by defining a new autocrine loop that involves GPR55, LPI and the ABC transporter, ABCC1, in prostate and ovarian cancer cell lines." (PMID 26784247, 2016). "In the present study, we have demonstrated that these ovarian carcinoma cell lines secrete LPI and induce in vivo CAM angiogenesis in a GPR55-dependent manner." (PMID 25989290, 2015). "The pharmacological GPR55 inhibitor CID16020046 inhibited LPI-stimulated ECFC proliferation, network formation and migration in vitro as well as ovarian carcinoma cell- and LPI-induced angiogenesis in vivo." (PMID 25989290, 2015).
ovarian carcinoma (continued). "Based on reports that LPI is produced and secreted by highly vascularized ovarian carcinomas, we decided to investigate the potential role of the LPI/GPR55 axis in promoting angiogenesis." (PMID 25989290, 2015). "In the present study, we demonstrated that ovarian cancer cells produced and secreted LPI which stimulated ECFC angiogenic potential in vitro and in vivo angiogenesis in the CAM in a GPR55-dependent manner via activation of the MAPK pathway." (PMID 25989290, 2015). "Furthermore, CBD was able to block GPR55-dependent signaling of LPI in prostate and ovarian carcinoma cells." (PMID 33802282, 2021). "These lipids are noticeably elevated in ascitic fluid obtained from ovarian cancer patients compared to non-malignant controls, suggesting a role for GPR55 in ovarian cancer." (PMID 34324032, 2021).
cholangiocarcinoma (7 papers, 2017 to 2023). A carcinoma that arises from the intrahepatic biliary tree (intrahepatic cholangiocarcinoma) or from the junction, or adjacent to the junction, of the right and left hepatic ducts (hilar cholangiocarcinoma). "Similar contradictory results were obtained by a previous study, demonstrating a growth inhibition of cholangiocarcinoma cell line Mz-ChA-1 when GPR55 became activated by AEA, an endocannabinoid that generally acts as an agonist at CB1 or CB2." (PMID 33802282, 2021). "Furthermore, AEA, an accepted agonist for CB1 and CB2, exerted anti-proliferative and pro-apoptotic effects on cholangiocarcinoma cells by activating GPR55, although GPR55 is thought to promote tumor cell proliferation of other tumor entities." (PMID 37998380, 2023). "However, it is noteworthy that GPR55 was observed to have antiproliferative and proapoptotic effects on cholangiocarcinoma cells." (PMID 35562947, 2022). "Thus, GPR55 was detectable in a number of tumor entities including melanoma, colon, breast, cholangiocarcinoma, prostate cancer, and GBM." (PMID 33802282, 2021). "Interestingly, not only was the treatment with AEA able to reduce cholangiocarcinoma cell proliferation in vitro and in vivo, but this effect was also observed with another GPR55 agonist, O-1602." (PMID 31611800, 2019). "Interestingly, pharmacological activation of GPR55 in cholangiocarcinoma cells, however, diminishes cancer cell proliferation through activation of JNK pathway, which can be blocked by GPR55 knockdown, suggesting that GPR55 may also act as a tumor suppressor." (PMID 36291926, 2022). "However, when GPR55 is activated by the endocannabinoid, AEA, cholangiocarcinoma cell survival is inhibited." (PMID 29066974, 2017).